BCR (BCR activator of RhoGEF and GTPase)
Diseases named in the same sentence as BCR in open-access papers (continued):
Sharing a sentence is not in itself a finding about the gene and the disease.
chronic myeloid leukemia (continued). "These mutations include the BCR-ABL fusion event, associated with chronic myeloid leukemia (CML) and acute lymphoblastic leukemia (ALL), and the BCL2-IGH and IGH-cMyc fusion events, associated with follicular non-Hodgkin lymphoma." (PMID 29300727, 2018). "Tyrosine kinase BCR-ABL fusion protein is the driver in patients with chronic myeloid leukemia (CML)." (PMID 29358661, 2018). "Imatinib is a tyrosine kinase inhibitor (TKI) that targets the oncogenic BCR-ABL fusion protein in chronic myelogenous leukemia (CML)." (PMID 30463359, 2018). "The development of ABL tyrosine kinase inhibitors that were originated against the oncogenic BCR-ABL protein for the treatment of chronic myeloid leukemia (CML) is the most successful example of molecular targeted therapy to date." (PMID 29774130, 2018). "Chronic myeloid leukemia (CML) is a clonal disease characterized by the presence of the constitutively active tyrosine kinase BCR-ABL oncoprotein." (PMID 30153828, 2018). "The BCR-ABL fusion protein in chronic myelogenous leukemia (CML) has been shown to be immunogenic, with the induction of specific T cells capable of lysing tumor cells expressing the BCR-ABL protein." (PMID 30149610, 2018). "Active BCR related (ABR) protein shares high homology with BCR (Breakpoint Cluster Region), which acts as a tumor suppressor in chronic myeloid leukemia and meningiomas." (PMID 29262589, 2017). "Chronic myeloid leukemia (CML) is a clonal malignant disease caused by the expression of BCR/ABL." (PMID 27999193, 2017). "Imatinib mesylate, which is an effective drug for the treatment of chronic myeloid leukemia by targeting the dysregulated tyrosine kinase BCR-ABL, inhibits the phosphorylation of DRP1Ser616 with an IC50 of 0.97 ± 0.3 μM." (PMID 29290987, 2017). "This translocation forms the fusion oncoprotein, a constitutionally active tyrosine kinase BCR-ABL, which has been causatively linked to the development of Chronic Myelogenous Leukemia (CML)." (PMID 28086219, 2017). "A previous study showed that BCR acts as a tumor suppressor in chronic myeloid leukemia and meningiomas." (PMID 29262589, 2017). "As such, silencing of Perk increased the therapeutic efficacy of treatments based on the depletion of amino acids in T cell leukemia, and sensitized chronic myeloid leukemia (CML) cells to the apoptosis induced by the BCR/ABL inhibitor, imatinib mesylate." (PMID 28105371, 2017). "We also tested the effects of AdPROM-mediated SHP2 degradation on MAPK signalling in K-562 chronic myelogenous leukaemia cells, which naturally harbour the BCR-Abl fusion." (PMID 28490657, 2017). "SETBP1 mutations have been identified in atypical chronic myeloid leukemia (aCML), which is a rare disorder of hematopoietic stem cells and shares clinical and laboratory features with CML but lacks the BCR-ABL fusion gene." (PMID 28533818, 2017). "This is different from other well-established fusions such as BCR-ABL in chronic myelogenous leukemia, TMPRSS2-ERG in prostate cancer, or EWS-FLI1 in Ewing’s sarcoma with junctional variability." (PMID 28978917, 2017). "The use of tyrosine kinase inhibitors (TKIs) that target BCR–ABL has markedly improved the outcomes in patients with chronic myeloid leukemia (CML)." (PMID 28184964, 2017). "A 67-year-old white man with chronic myelogenous leukemia was treated with the dual Src and BCR-ABL tyrosine kinase inhibitor dasatinib." (PMID 29287600, 2017). "Chronic myeloid leukemia is determined by a reciprocal translocation between chromosomes 9 and 22, resulting in the formation of the chimeric BCR/Abl protein (hereafter “BCR/Abl”) that functions as a constitutively active tyrosine kinase." (PMID 27148487, 2016). "Mouse progenitor 32D cells transfected with the BCR-ABL chimerical cDNA were used as a chronic myelogenous leukemia progenitor model and were also arrested in the G2/M phase after 18 or 24 h of treatment with curcumin 20μM." (PMID 27832139, 2016).
chronic myeloid leukemia (continued). "This cell line was derived from a BCR–ABL translocation‐positive blast‐crisis chronic myeloid leukaemia and is an established cell‐line model for leukaemia." (PMID 27347458, 2016). "Transformation of hematopoietic stem cells by the BCR-ABL fusion oncogene leads to development of chronic myeloid leukemia (CML)." (PMID 27384990, 2016). "Another attribute of some well-known oncogenes, such as BCR-ABL fusion in chronic myeloid leukemia or mutant EGFR or KRAS in LUAD, is the dependence on sustained expression of those oncogenes for the maintenance of cell growth or viability." (PMID 27776121, 2016). "A well-known example is the reciprocal translocation between chromosome 9 and 22 resulting in expression of the BCR-ABL fusion protein in chronic myeloid leukemia." (PMID 26177635, 2015). "Chronic myeloid leukemia (CML) is a myeloproliferative disorder characterized by BCR-ABL fusion gene." (PMID 25575817, 2015). "Chronic myeloid leukemia (CML) is a malignant hematopoietic stem cell disease characterized by the presence of Philadelphia chromosome, t(9:22)(q34:q11), resulting in the BCR-ABL fusion gene which encodes for a constitutively activated tyrosine kinase." (PMID 26000313, 2015). "For example, the BCR-ABL fusion oncogene was reported to control the expression of MICA in chronic myelogenous leukemia cells at the posttranscriptional level." (PMID 24860567, 2014). "The human K562 cell line was established from a chronic myelogenous leukemia patient that expresses the BCR/ABL fusion gene." (PMID 25115845, 2014). "Chronic myeloid leukemia (CML) is characterized by the presence of a BCR-ABL fusion gene, which is the result of a reciprocal translocation between chromosomes 9 and 22 (Philadelphia (Ph) chromosome)." (PMID 24963404, 2014). "The break point cluster–Abelson tyrosine kinase (BCR–ABL) oncogene is formed in patients with chronic myeloid leukemia and acute lymphoblastic leukemia by fusing the BCR gene on chromosome 22 and the ABL tyrosine kinase on chromosome 9." (PMID 24926233, 2014). "SPHK1 expression is up-regulated by the BCR/Abl translocation that is characteristic of chronic myeloid leukaemia, and signalling through the S1P2 receptor stabilises the oncogenic BCR/Abl fusion protein." (PMID 24970218, 2014). "We demonstrate this method by detecting the BCR-ABL fusion transcripts that occur in chronic myeloid leukemia cells, and by detecting the EWSR1-FLI1 fusion transcripts that occur in Ewing's sarcoma cells." (PMID 24675777, 2014). "In contrast, cancers such as chronic myeloid leukemia and prostate cancer can be stratified by a cancer type-specific fusion such as BCR-ABL and TMPRSS2-ERG respectively." (PMID 24675677, 2014). "Chronic myeloid leukemia (CML) is characterized by the formation of Philadelphia chromosome and the generation of BCR-ABL fusion gene to encode the oncoprotein with deregulated tyrosine kinase activity." (PMID 24465953, 2014). "For example, the BCR-ABL fusion gene in chronic myeloid leukemia is known to initiate oncogenesis through the formation and mis-regulation of a fusion protein." (PMID 24675677, 2014). "Chronic myeloid leukemia (CML) results from the clonal expansion of pluripotent hematopoietic stem cells containing the active BCR/ABL fusion gene produced by a reciprocal translocation of the ABL1 gene to the BCR gene." (PMID 24634785, 2014). "Chronic myeloid leukemia (CML) is a neoplastic disease of hematopoietic stem cells triggered by the oncogene BCR-ABL." (PMID 25426931, 2014). "Dasatinib is a compound developed for chronic myeloid leukemia as a multi-targeted kinase inhibitor against wild-type BCR-ABL and SRC family kinases." (PMID 24918603, 2014). "Chronic myelogenous leukemia (CML), which is characterized by the presence of the fusion tyrosine kinase BCR-ABL, is associated with altered cell interaction with extracellular matrix proteins." (PMID 25198091, 2014).
chronic myeloid leukemia (continued). "An example is the use of Gleevec and other Abl kinase inhibitors in chronic myelogenous leukemia (CML) patients that harbor the Philadelphia Chromosome translocation creating a BCR-Abl gain of function fusion protein." (PMID 24904423, 2014). "Chronic myeloid leukemia (CML) is a myeloproliferative disease resulting from the clonal hematopoietic stem cell disorder that is caused by the transformation of oncogenic breakpoint cluster region-Abelson (BCR-ABL) fusion gene." (PMID 24967705, 2014). "Imatinib mesylate (Gleevec, STI571), an inhibitor of ABL, PDGFRα, and KIT tyrosine kinases, is successfully applied to the treatment of BCR-ABL-positive chronic myelogenous leukemia (CML)." (PMID 25431951, 2014). "As the known oncomir, miR-17∼92, is regulated by BCR-ABL fusion in chronic myeloid leukaemia, we investigated its role in BCR-ABL translocated ALL." (PMID 24280866, 2014). "Imatinib (Gleevec®), an inhibitor designed to target the BCR-ABL fusion complex in chronic myelogenous leukemia (CML), was the first successful drug in this category and exemplifies the therapeutic potential of these drugs." (PMID 24885928, 2014). "Chronic myeloid leukemia is a clonal myeloproliferative disorder disease in which BCR/ABL plays an important role as an oncoprotein and molecular target." (PMID 24257075, 2013). "Chronic myeloid leukemia (CML) is a hematological malignancy that arises from the transformation of stem hematopoietic cells by the fusion oncogene BCR/ABL and subsequent clonal expansion of BCR/ABL-positive progenitor leukemic cells." (PMID 23965958, 2013). "For example, chronic myelogenous leukemia (CML) cells dependence on BCR-ABL tyrosine kinase is induced by a chromosomal translocation only in the malignant cells, making Gleevec a selective and effective treatment for CML." (PMID 23471124, 2013). "In contrast, in chronic myeloid leukemia, the initiating event is represented by BCR-ABL, while in several other myeloid cancers the initiating events are PDGFR translocations, so therapy in those cases would target in the initiating events." (PMID 23998913, 2013). "Gene fusions, like BCR/ABL1 in chronic myelogenous leukemia, have long been recognized in hematologic and mesenchymal malignancies." (PMID 23637631, 2013). "Deregulated BCR-ABL tyrosine kinase activity is the molecular marker for chronic myeloid leukemia (CML)." (PMID 23652925, 2013). "One such example is Imatinib mesylate (Gleevec), a tyrosine kinase inhibitor which was developed to inhibit tyrosine kinase BCR-ABL in chronic myeloid leukemia (CML)." (PMID 22927846, 2012). "Chronic myeloid leukemia (CML) is a hematopoietic stem cell malignancy with a hallmark cytogenetic abnormality, i.e., the BCR-ABL fusion oncogene, resulting from the reciprocal translocation of chromosomes 9 and 22 [also known as Philadelphia (Ph) chromosome]." (PMID 22995644, 2012). "Chronic myeloid leukemia (CML) is a stem cell disease in which BCR/ABL plays an important role as an oncoprotein and a molecular and immunogenic target." (PMID 23241263, 2012). "The BCR gene harbors two common breakpoints involved in the formation of the two alternative forms of the Philadelphia chromosome translocation seen in chronic myeloid leukemia and acute lymphoblastic leukemia ‐." (PMID 22549126, 2012). "Chronic myeloid leukemia (CML) was characterized by Philadelphia (Ph) chromosome that generates a unique BCR-ABL fusion gene." (PMID 22606351, 2012). "This approach is best exemplified by the use of Gleevec to block the activation of the BCR-ABL fusion kinase in chronic myelogenous leukemia." (PMID 22091388, 2011). "The constitutively activated BCR-ABL tyrosine kinase of chronic myeloid leukemia (CML) is localized exclusively to the cytoplasm despite the three nuclear localization signals (NLS) in the ABL portion of this fusion protein." (PMID 21347248, 2011).
chronic myeloid leukemia (continued). "In patients with chronic myeloid leukemia, tyrosine kinase inhibitors suppress the BCR-ABL+ clone and often induce complete molecular remissions." (PMID 21624109, 2011). "A BCR/ABL-MAPKERK1/2-PCBP2 pathway was established in myeloid chronic myelogenous leukemia blast crisis (CML-BC) progenitors." (PMID 22022391, 2011). "Chronic myeloid leukaemia (CML) is provoked by the BCR-ABL translocation which leads to clonal myeloid cell expansion." (PMID 21789194, 2011). "Both the RAS-RAF-MEK-ERK1/2 and PI3K/Akt pathways are activated downstream of the chronic myeloid leukaemia BCR-ABL fusion protein." (PMID 19935796, 2010). "As proof-of-concept we used the BCR-ABL fusion product that is of paramount importance in chronic myeloid leukemia, showing the application potential in cancer diagnosis." (PMID 20181241, 2010). "Chronic myeloid leukemia (CML) is associated with the Philadelphia chromosome, which results from a reciprocal translocation between chromosomes 9 and 22 generating the BCR-ABL fusion oncogene." (PMID 19749982, 2009). "Chronic myeloid leukemia (CML) cells express an oncogene protein consisting of the gene fusion of BCR (Breakpoint Cluster Region) and the tyrosine kinase ABL (Abelson), which behaves as a potent inhibitor of apoptosis." (PMID 19430526, 2009). "The dependence of chronic myeloid leukemia (CML) on the translocated BCR-ABL kinase is correlated with dramatic responses to small molecule inhibitors." (PMID 19714203, 2009). "BCR-ABL: Fusion of the BCR (breakpoint cluster region) gene on Chromosome 22 to the ABL (Ableson leukemia virus) gene on Chromosome 9 is found in 95% of patients with chronic myeloid leukemia." (PMID 17973575, 2007). "The complexes were tested for antiproliferative activitiy on the chronic myeloid leukemia-derived K-562, overexpressing the BCR-ABL fusion protein." (PMID 18274603, 2007). "For example, the protein kinase inhibitor imatinib (Gleevec) was designed to treat chronic myelogenous leukemia (CML) based on knowledge of the causative molecular defect—translocation and dys-regulated BCR–ABL kinase." (PMID 17319736, 2007). "Chronic myelogenous leukemia is believed to originate when a single hematopoietic stem cell acquires a Ph chromosome carrying the BCR/ABL fusion gene." (PMID 22792021, 2006). "In chronic myeloid leukaemia, it has been shown that expression of the p210 BCR-ABL fusion protein leads to a downregulation of BRCA1 protein expression, owing to post-transcriptional mechanisms." (PMID 17047656, 2006). "Another gene down-regulated after Lhx2 expression is turned off is Prkd2 (Protein kinase D2), which has also been shown to be a substrate for the BCR-ABL fusion protein present in chronic myeloid leukemia cells." (PMID 16600034, 2006). "Vaccination trials of fusion gene-derived peptides have been reported with BCR-ABL in 12 patients with chronic myelogenous leukemia, EWS-FLI1 in 12 patients with Ewing's sarcoma, and PAX3-FKHR in four patients with alveolar rhabdomyosarcoma." (PMID 15647119, 2005). "This study confirms the central oncogenic role of BCR–ABL in the pathogenesis of chronic myeloid leukaemia, and highlights the role of targeting this tyrosine kinase as a useful tool in the clinical management of the disease." (PMID 11986783, 2002). "Chronic myeloid leukaemia is typically characterised by the presence of dysregulated BCR–ABL tyrosine kinase activity, which is central to the oncogenic feature of being resistant to a wide range of cytotoxic agents." (PMID 11986783, 2002). "Identification of Philadelphia chromosome or BCR/ABL gene rearrangement in chronic myeloid leukemia is important at diagnosis as well as after treatment." (PMID 11175620, 2001).
chronic myeloid leukemia (continued). "Using BCR::ABL1 monitoring in chronic myeloid leukemia as a case study, we aligned measurements to 90-day intervals, applied a windowed, uncertainty-propagating imputation strategy, and trained recurrent neural network (RNN) and XGBoost models to forecast values three and six months ahead." (PMID 41542066, 2026). "A classical example is the BCR::ABL1 fusion in chronic myeloid leukemia (CML)." (PMID 40725438, 2025). "In 2001, imatinib, the first-in-class tyrosine kinase inhibitor (TKI), was approved by the Food and Drug Administration (FDA) for treatment of mutated BCR-ABL (breakpoint cluster region (BCR) and abelson murine leukemia viral oncogene homolog 1 (ABL1)) chronic myeloid leukemia (CML)." (PMID 41402855, 2025). "Chronic myeloid leukaemia (CML), a myeloproliferative disorder, is caused by a chromosomal translocation that results in a fusion of two genes, the breakpoint cluster region protein (BCR) gene on chromosome 22 and the Abelson murine leukaemia viral oncogene homolog 1 (ABL1) gene on chromosome 9." (PMID 39009935, 2025). "Data on FR expression in BCR::ABL1-positive chronic myeloid leukemia (CML) is scarce." (PMID 39847116, 2025). "Two meaningful successes in this field include the approval of Trastuzumab (Herceptin; Genentech) in 1988 for treating HER2-positive metastatic breast cancer patients, and Imatinib (Gleevec; Novartis) in the early 2000s to treat chronic myeloid leukemia (CML) by targeting BCR-ABL tyrosine kinase." (PMID 39747667, 2025). "Similarly, mutations in the HER2 or BCR-ABL kinase domain, like T315I, result in resistance in breast cancer and chronic myeloid leukemia (CML), respectively." (PMID 40427686, 2025). "Significance: The PROTAC SIAIS562055 sustainably degrades SOS1 and inhibits downstream ERK signaling, showing strong antiproliferative activity and synergistic effects with KRAS inhibitors in KRAS-mutant cancers and BCR–ABL inhibitors in chronic myeloid leukemia." (PMID 39437162, 2025). "With the discovery of the Philadelphia chromosome and the development of the BCR-ABL tyrosine kinase inhibitor (TKI) imatinib in chronic myeloid leukemia (CML) at the turn of the twenty-first century, precision oncologic approaches were realized in the treatment of HRMNs." (PMID 39997326, 2025). "Chronic myeloid leukemia (CML) is a blood tumor driven by the BCR-ABL fusion gene." (PMID 40427609, 2025). "Chronic myeloid leukemia, a BCR::ABL-positive MPN, may occasionally present with thrombocytosis but is distinguished by its molecular hallmark." (PMID 41552126, 2025). "In this view, we assumed that any kind of treatment administered before a confirmed diagnosis of chronic myeloid leukemia might change the amount of BCR::ABL1 transcript levels." (PMID 40076467, 2025). "Chronic myeloid leukemia (CML) is a hematological neoplasm initiated by the fusion gene BCR-ABL." (PMID 39026664, 2024). "One of the most well-known outcomes of chromosome 22 rearrangements is the genesis of Philadelphia chromosome in which the reciprocal translocation between chromosome 22 and chromosome 9 results in the formation of the BCR::ABL fusion gene, a hallmark of chronic myeloid leukemia (CML)." (PMID 39769457, 2024). "Chronic myeloid leukemia (CML) is a hematopoietic malignancy driven by the fusion gene BCR::ABL1." (PMID 37880985, 2024). "Additionally, targeting HSPA8 by downregulating BCR-ABL can enhance the chemotherapy sensitivity of chronic myeloid leukemia cells." (PMID 38420434, 2024). "Chronic myelogenous leukemia (CML) is a hematopoietic malignancy caused by reciprocal translocation of chromosomes 9 and 22 in myeloid cells that generate an oncogenic fusion protein BCR/ABL1,2." (PMID 38368446, 2024). "The BCR gene, located on chromosome 22, is most known as the breakpoint for chromosomes 22 and 9 reciprocal translocation, which produces the Philadelphia chromosome and is common in patients with chronic myelogenous leukemia." (PMID 37730603, 2023).